MBD4 (methyl-CpG binding domain 4, DNA glycosylase)
Diseases named in the same sentence as MBD4 in open-access papers (continued):
Sharing a sentence is not in itself a finding about the gene and the disease.
colorectal adenoma (2 papers, 2022 to 2024). An adenoma that arises from the colon or rectum. "The mutation spectrum was almost exclusively attributable to COSMIC mutational signature SBS112 in colorectal adenomas from individuals with MBD4 deficiency, in contrast to sporadic colorectal adenomas." (PMID 35460607, 2022). "The colorectal adenomas from MBD4-deficient individuals showed a mutator phenotype attributable to mutational signature SBS1, consistent with the function of MBD4." (PMID 35460607, 2022). "Most individuals with bi-allelic LOF variants in MBD4 developed multiple colorectal adenomas and an extracolonic neoplasm." (PMID 35460607, 2022). "Next, we undertook targeted sequencing of MBD4 in replication cohorts comprising a total of 1,611 individuals with at least ten colorectal adenomas, familial or early onset CRC, or CRC in combination with other tumors." (PMID 35460607, 2022).
cutaneous melanoma (2 papers, 2020 to 2024). A primary melanoma arising from atypical melanocytes in the skin. "The high TMB in iris UM reported here suggests they are more likely to respond to immunotherapy, given the observations for MBD4 germline UM patients, who have high TMB, a predictor of response to immunotherapy response in cutaneous melanoma and other cancers." (PMID 32415113, 2020).
Fanconi anemia (2 papers, 2015 to 2024). Fanconi anemia (FA) is a hereditary DNA repair disorder characterized by progressive pancytopenia with bone marrow failure, variable congenital malformations and predisposition to develop hematological or solid tumors. "Dysregulation of genes related to NER (FANCB and FANCD2), BER (MBD4), and Fanconi anemia (FANCB and FANCD2) was also observed." (PMID 39728796, 2024).
iris melanoma (2 papers, 2021 to 2025). A uveal melanoma that arises from the iris. "We did not detect MBD4 mutations in any of the tumors in the present study, and only the iris melanoma had high TMB." (PMID 34453044, 2021).
melanoma (2 papers, 2019 to 2020). A malignant, usually aggressive tumor composed of atypical, neoplastic melanocytes. "Some are well known and strongly associated, like CDKN2A for melanoma, while others are rare (MBD4) or more controversial, like BRCA1/2." (PMID 31382694, 2019).
renal cell carcinoma (2 papers, 2023 to 2025). "Specifically, MBD2 has been shown to promote the progression and poor prognosis of renal cell carcinoma, while MBD4 has been associated with cervical cancer polymorphism." (PMID 37370795, 2023). "We searched novel genetic associations for predisposition to UM, additional to already studied BAP1 and MBD4, by using targeted amplicon sequencing of 19 genes associated with UM, BAP1, or renal cell carcinoma in 270 consecutively enrolled Finnish patients with UM." (PMID 39344744, 2025).
schizophrenia (2 papers, 2012 to 2013). A major psychotic disorder characterized by abnormalities in the perception or expression of reality. "Though lack of MBD4 does not lead to defects in mice, it has been found that MBD4 mRNA levels are significantly up-regulated in the hippocampus of both schizophrenia and bipolar disorders suggesting a potential involvement of this glycosylase in human neurodegenerative diseases." (PMID 23203191, 2012).
adenoma (1 paper, 2022). A neoplasm arising from the epithelium. "Overall, 88% of driver mutations in adenomas from individuals with MBD4 deficiency were CpG>TpG transitions compared to only 37% in sporadic adenomas." (PMID 35460607, 2022). "The driver genes mutated in MBD4-deficient adenomas were similar to those in sporadic adenomas and CRCs." (PMID 35460607, 2022). "MBD4-deficient adenomas harbored fewer KRAS mutations (three of 19 adenomas) than sporadic tumors (Fisher’s exact, p = 0.0028) but significantly more somatic mutations in AMER1 (MIM: 300647) (12 of 19 adenomas; Fisher’s exact, p = 0.039)." (PMID 35460607, 2022).
autism (1 paper, 2013). Persistent deficits in social interaction and communication and interaction as well as a markedly restricted repertoire of activity and interest as well as repetitive patterns of behavior. "TRIM27 is a DNA-binding protein associated with the nuclear matrix and interacts with methyl-CpG-binding domain (MBD) proteins, including MBD2, MBD3 and MBD4, and rare autism-specific protein-changing alterations have been observed both in MBD3 and MBD4." (PMID 24047820, 2013).
breast tumors (1 paper, 2016). "Although a role for Mbd4 in active demethylation remains controversial, a recent study has linked abnormal expression of Mbd4 in breast tumors with aberrant CpG methylation and metastasis, suggesting that alternative functions of Mbd4 could in principle influence carcinogenesis." (PMID 27086921, 2016).
chronic hepatitis B (1 paper, 2019).
ciliopathy (1 paper, 2022). A genetic disorder of the cellular cilia or the cilia anchoring structures, the basal bodies, or of ciliary function. "Eight of the 140 potential ciliopathy genes had predicted secondary interaction with gold standard cilia proteins, Aplnr, Casr, Gcgr, Grm6, Med1(or Mbd4), Mlh1, Rxfp2, and Wdr62.." (PMID 36456625, 2022). "In addition, 7 genes had primary interactions with the 24 directly interacting potential ciliopathy genes and thus had secondary interactions with known cilia proteins: Aplnr, Casr, Gcgr, Grm6, Med1(or Mbd4), Mlh1, and Rxfp2." (PMID 36456625, 2022).
colitis (1 paper, 2016). Inflammation of the colon. "In particular, our finding that Mbd4 deficiency exacerbates the course of experimental colitis suggests that MBD4 status may serve as a useful prognostic indicator for management of ulcerative colitis in human patients." (PMID 27086921, 2016).
eosinophilia (1 paper, 2023). "The MBD4-null dam developed sustained eosinophilia later in life, but we saw no other signs of neoplastic processes associated with MBD4 loss of function in humans nor any obvious disease in the hypermutated offspring." (PMID 37984997, 2023).
glioblastoma (1 paper, 2018). The most malignant astrocytic tumor (WHO grade IV). "Here we present three patients with hypermutated CpG>TpG tumors (two UM and one glioblastoma) associated with MBD4 germline deleterious mutations and somatic inactivation in the tumors." (PMID 29760383, 2018). "Of these 20 cases, patient GBM_4 presented a glioblastoma carrying 1149 SNVs (440 non-synonymous SNVs) and a germline c.335+1G>A:p.R83Pfs*5 MBD4 mutation with somatic loss of heterozygosity leading to the use of a cryptic splice donor site, loss of 88 bases, and a premature stop codon." (PMID 29760383, 2018). "The three other hypermutated CpG>TpG glioblastoma cases did not carry any identifiable deleterious MBD4 or TDG mutation." (PMID 29760383, 2018).
lymphoma (1 paper, 2015). A malignant (clonal) proliferation of B- lymphocytes or T- lymphocytes which involves the lymph nodes, bone marrow and/or extranodal sites. "Specifically, Mbd4−/−Mlh1−/− mice developed lymphomas at a higher incidence (83%) than Mlh1−/− mice (52%), but this difference was not statistically significant (Fisher's exact test p = 0.35)." (PMID 26503472, 2015). "Early lymphomas were found in 20% of Mbd4−/−Mlh1+/+ and 4% of Mbd4 wild type, single and double heterozygous mice; lymphoid hyperplasia was found in 15% and 13% of Mbd4−/−Mlh1+/+ and the remaining cohort, respectively." (PMID 26503472, 2015). "Specifically, lymphomas were identified in 30% of Mbd4−/−Mlh1+/+ mice, a frequency marginally higher than that of mice with the other genotypes (26%)." (PMID 26503472, 2015). "We found that Mbd4 and Mlh1 double knockout mice showed a significant survival reduction and increased incidence of high-grade lymphomas compared with Mlh1 single knockout mice." (PMID 26503472, 2015). "The relatively high incidence of lymphoma, early lymphoma and lymphoid hyperplasia in Mbd4−/− mice may be due to the role of this gene in Immunoglobulin CSR." (PMID 26503472, 2015).
metastatic colorectal cancer (1 paper, 2017). "Another micro RNA miR-224 has been shown to target MBD4 in metastatic colorectal cancer cells." (PMID 28233878, 2017).
neuroblastoma (1 paper, 2017). Neuroblastoma (NB) is the most common solid, extracranial childhood tumor. "These assays using cultured neuroblastoma cells revealed that MBD4 does indeed control PNMA5 gene expression by binding to the methylated site of the PNMA5 promoter." (PMID 27706918, 2017).
polyp (1 paper, 2016). A usually exophytic mass attached to the underlying tissue by a broad base or a thin stalk. "However, comparing the AOM/DSS assays carried out with the non-transplanted and transplanted mice, the polyp multiplicity at time of death was not significantly different between transplanted and non-transplanted Mbd4−/− mice (p > 0.74)." (PMID 27086921, 2016).
tumor predisposition syndrome (1 paper, 2023). "MBD4 is critical for genome stability and preventing mutations, and loss of function of MBD4 has recently been associated with a higher risk of MBD4-associated neoplasia syndrome, a multiorgan tumor predisposition syndrome." (PMID 37984997, 2023).
Wilson disease (1 paper, 2017). A very rare inherited multisystemic disease presenting non-specific neurological, hepatic, psychiatric or osseo-muscular manifestations due to excessive copper deposition in the body. "In summary, introducing a larger amino acid (Asp or Val instead of Gly) at position 386 in MBD4 (as found in MBD1 and MBD6 in Wilson disease patients) results in enhanced domain structural dynamics in silico and decreased resistance towards thermal perturbations in vitro." (PMID 27744583, 2017).
tumor (39 papers, 2000 to 2025). "In these cases, the associated tumours show loss of the wildtype MBD4 allele and, like in neoplasms from individuals with MANS, showed elevated tumour mutation burden enriched in CpG > TpG mutations (signature SBS1/SBS96)." (PMID 40237887, 2025). "We and others have shown that individuals with constitutive deficiency in the BER protein MBD4, which corrects T:G mismatches, develop tumours with a very high CpG > TpG mutation burden and a predominant mutational signature that is very similar to SBS1." (PMID 40855317, 2025). "The MBD4 (Methyl-CpG Binding Domain 4, DNA Glycosylase) gene encodes an enzyme that plays a crucial role in DNA repair and acts as a tumor-suppressor gene." (PMID 37628989, 2023). "For example, deleterious MBD4 mutations are associated with a higher tumor mutation burden and a hypermutator phenotype." (PMID 36982149, 2023). "MBD4 maps to chromosome 3 and is a predisposing tumor suppressor gene for UM associated with hypermutated tumors with LOH3." (PMID 36077643, 2022). "Encoding a glycosylase integral to DNA repair, it is suggested that defective MBD4 leads to increased tumor mutational burden, which in turn enhances the efficacy of immune checkpoint inhibitors." (PMID 36497270, 2022). "We show in this co-clinical model that the use of gemcitabine (a cytidine analog) leads to a dramatic response of MBD4-deficient UM on tumor progression." (PMID 36323843, 2022). "The MBD4 gene encodes a DNA glycosylate and is another tumor suppressor gene located on chromosome 3." (PMID 34771666, 2021). "Here, the authors report the whole genome sequence of 103 uveal melanomas and find that the tumour mutational burden is variable and that two subsets of tumours are characterised by MBD4 mutations and a UV exposure signature." (PMID 32415113, 2020). "Rare UM with specific germline MBD4 mutations has been described to respond to anti-PD-1 therapy, probably because MBD4 mutations are associated with a high tumour mutation burden." (PMID 32998469, 2020). "Closer inspection confirmed a germline MBD4 mutation in the patient, with concomitant loss of the wild-type parental allele in the tumor." (PMID 31624251, 2019). "We identified a germline deleterious frameshift deletion of MBD4 (3q21.3; c.1441delT:p.F481Dfs*9) with loss of the second allele by monosomy 3 in all tumor samples." (PMID 29760383, 2018). "Although Mbd4-null mice do not have increased rates of spontaneous tumorigenesis, a null mutation in Mbd4 on the ApcMin/+ cancer prone background confers a further decrease in survival time and greater tumor multiplicity relative to the ApcMin/+ single mutant." (PMID 27086921, 2016). "A test of association between pathogenic MBD4 variants and presence of tumor was highly significant (Fisher's exact test p-value <0.0001)." (PMID 26503472, 2015). "Consistent with a possible pathogenic role, our detailed histological analysis revealed that Mbd4 modifies the tumor spectrum associated with the Mlh1 defect leading to more aggressive tumors." (PMID 26503472, 2015). "Whereas MBD4 frameshifts were only detected in tumors, missense variants were found in both normal and tumor DNA." (PMID 26503472, 2015). "For example, increased mutations at CpG sites (CpG to TpG) and enhanced tumor formation has been reported in MBD4−/− mice." (PMID 22952798, 2012). "The agreed sequence of events in human tumours involves a mutational event that leads to an MMR gene abnormality thus causing the MSI phenotype that then by chance hits an MBD4 allele." (PMID 17285135, 2007). "In addition, evidence suggests that patients with MBD4 mutations respond to immune checkpoint blockade, likely due to the increased tumour mutational burden produced by the defect which causes wide-scale deamination of 5-methylcytosine (CpG to TpG)." (PMID 35190695, 2022).
tumor (continued). "Here, we hypothesize that the difference in DNA metabolism consecutive to MBD4 deficiency may result in specific cytotoxicities in MBD4-deficient tumor cells in a synthetic lethality fashion." (PMID 36323843, 2022). "In parallel, tumor progression was evaluated in the UM MBD4-deficient patient." (PMID 36323843, 2022). "MBD4 mutations result in a CpG > TpG hypermutator phenotype with a high tumor mutation burden, which may explain the immunotherapy responsiveness." (PMID 34771666, 2021). "Clinical trials using immunotherapy in MUM patients may want to consider stratifying for MBD4 mutations given the high tumor mutation burden of these tumors and likelihood of response to immune checkpoint inhibitors." (PMID 34771666, 2021). "C:G to T:A transition mutations in tumor suppressor genes are a frequent feature of human cancers, suggesting that Mbd4-mediated repair may be important for suppressing carcinogenesis in chronically inflamed tissues." (PMID 27086921, 2016). "Thus, loss of Mbd4 function confers increased tumor susceptibility and a more severe outcome when combined with the cancer-predisposing Mlh1−/− background." (PMID 26503472, 2015). "Although mutation in MBD4 is thought to occur in MSI tumours as a consequence of the microsatellite instability caused by mismatch repair (MMR) protein inactivation, we have postulated that MBD4 mutation may still affect tumour progression in humans." (PMID 17285135, 2007). "In microsatellite unstable tumours MBD4 can itself be mutated at an exonic polynucleotide tract." (PMID 11104560, 2000). "Furthermore, we highlight recent advances in identifying predictive biomarkers—such as genetic mutations (e.g., BAP1, MBD4), immune gene signatures, circulating tumor DNA, and protein-based blood markers—that may facilitate patient stratification and treatment selection." (PMID 40661151, 2025). "Most UVM had a low tumor mutation burden (TMB), but two subsets with high TMB were identified: one driven by germline MBD4 mutation and another by ultraviolet radiation (UVR) exposure, which was restricted to iris UVM." (PMID 37509183, 2023). "Further, MBD4 was expressed more frequently in tumor immune microenvironment and tumor immunotherapy response groups than in non-response groups." (PMID 36425533, 2022). "A relationship was then investigated between MBD4 gene expression, IDH mutation status, and tumor mutation burden (TMB) in TCGA-GBM." (PMID 36425533, 2022). "Inclusion of MBD4 in genetic testing for polyposis and multi-tumor phenotypes is warranted to improve disease management." (PMID 35460607, 2022). "Rare marked response to immunotherapy has been reported in UM, and molecular investigation of these tumors revealed high tumor mutation burden (TMB) secondary to germline, loss‐of function MBD4 mutations." (PMID 33724676, 2021). "While most UM have low tumour mutation burden (TMB), two subsets with high TMB are seen; one driven by germline MBD4 mutation, and another by ultraviolet radiation (UVR) exposure, which is restricted to iris UM." (PMID 32415113, 2020). "Altogether, these data suggest an ongoing MBD4-related mutagenic process during tumor progression, as has been observed with APOBEC in other cancers." (PMID 29760383, 2018).